FAM204A (family with sequence similarity 204 member A)
Synonyms: C10orf84; FLJ13188; bA319I23.1
Tractability: PROTAC: ubiquitination databases record sites on it.
Gene: Protein-coding gene on chromosome 10 (118,297,925 to 118,342,331, reverse strand). Ensembl gene ENSG00000165669.
Subcellular location (Human Protein Atlas): Nucleoli; Nucleoplasm
Gene Ontology:
Molecular function: protein binding
Genetic constraint (gnomAD): Loss-of-function variants: 14 observed, 27.91 expected, observed/expected ratio (o/e) 0.5, 90% interval 0.33 to 0.78. The upper end of that interval is the gene's LOEUF score, 0.78, which puts it in group 3 of 6, group 1 being the genes least tolerant of losing a copy. Missense variants: 233 observed, 250.39 expected, observed/expected ratio (o/e) 0.93, 90% interval 0.83 to 1.04. Synonymous variants: 70 observed, 82.59 expected, observed/expected ratio (o/e) 0.85, 90% interval 0.7 to 1.03.
Homologues: Orthologues: chimpanzee FAM204A (99% identical), macaque FAM204A (97% identical), dog FAM204A (83% identical), guinea pig FAM204A (81% identical), mouse Fam204a (79% identical), rat Fam204a (76% identical), pig FAM204A (65% identical), tropical clawed frog fam204a (42% identical), zebrafish fam204a (42% identical).
Diseases named in the same sentence as FAM204A in open-access papers:
FAM204A is named in the same sentence as 2 diseases in open-access papers, as found by Europe PMC text mining. Sharing a sentence is not in itself a finding about the gene and the disease. The quoted sentences say what the papers report.
glioma (1 paper, 2022). A benign or malignant brain and spinal cord tumor that arises from glial cells (astrocytes, oligodendrocytes, ependymal cells). "The qRT-PCR results showed that the mRNA expression levels of FAM204A and SMU1 in human glioma cell lines overall showed a downward trend compared with the HA1800, while the mRNA expression levels of TNPO1 and TOP2A showed an overall upward trend." (PMID 35093128, 2022). "Compared with non-tumor tissues, FAM204A was down-regulated, but TNPO1 and TOP2A were up-regulated in glioma tissues." (PMID 35093128, 2022).
tumor (1 paper, 2022). "Compared with non-tumor brain tissue, the transcription levels of FAM204A and SMU1 in LGG tissues decreased, while the transcription levels of NPO1 and TOP2A increased." (PMID 35093128, 2022). "We selected four LLPS-related hub genes (FAM204A, SMU1, TNPO1 and TOP2A) involved in LPRS to test their transcript levels in cell lines, LGG tissues and non-tumor brain tissues." (PMID 35093128, 2022).